ITGA2 (integrin subunit alpha 2)
Diseases named in the same sentence as ITGA2 in open-access papers (continued):
Sharing a sentence is not in itself a finding about the gene and the disease.
glioblastoma (15 papers, 2009 to 2025). The most malignant astrocytic tumor (WHO grade IV). "ITGA2 has been identified as a key downstream target of BMI1 in CD133+ glioblastoma stem cells (GBM-SCs), regulating the characteristics of GBM stem cells." (PMID 39239559, 2024). "Furthermore, elevated ITGA2 expression has been observed in glioblastoma CSCs compared to their differentiated counterparts." (PMID 40316546, 2025). "In addition, in silico analyses of ITGA2 expression from low-grade gliomas (LGG, n = 515) and glioblastomas (GBM, n = 159) indicated that the higher expression of ITGA2 in LGG was associated with poor overall survival (P < 0.0001)." (PMID 35936750, 2022). "Furthermore, antibody blockade of ITGA2 potently inhibits glioblastoma cell migration." (PMID 39126040, 2024). "Finally, another possible therapeutic approach for ITGA2 would be nanotherapeutics; Guo and collaborators showed that designing ITGA2 antibody-coated nanoparticles containing cytotoxic drugs highly improved drug delivery and cell death in preclinical models of glioblastoma." (PMID 36765586, 2023). "Furthermore, we analyzed the potential impact of ITGA2 on the overall survival of GBM patients using the same database (a cohort of 540 patients, Datasheet: Tumor Glioblastoma-TCGA-540-MAS5.0-u133a)." (PMID 30996239, 2019). "Consistent with our results, ITGA2 was found to be significantly upregulated in both the glioblastoma tumor tissues and cell lines, with minimal expression in normal tissues." (PMID 39126040, 2024). "It has been reported that ITGA2 is expressed more significantly in glioblastoma compared with normal glial cells, and targeting ITGA2 through monoclonal antibody could impede the migration of glioblastoma cells, but not their proliferation." (PMID 31620367, 2019).
colorectal cancer (14 papers, 2016 to 2025). A primary or metastatic malignant neoplasm that affects the colon or rectum. "Recently, studies showed that aberrant expression of ITGA2 was associated with metastatic behavior in breast cancer, liver cancer, and colorectal cancer." (PMID 32232000, 2020). "Additionally, an independent investigation corroborated the role of ITGA2 as a diagnostic marker for liver metastasis in colorectal cancer." (PMID 39568561, 2024). "Interestingly, ITGA2 was a senescence associated inflammatory factor in colorectal cancer, while GBP1 was an interferon-responsive gene in innate immunity." (PMID 35169119, 2022). "Current evidence substantiates the role of ITGA2 as a tumor marker for colorectal cancer (CRC), contributing to its malignant biological phenotype." (PMID 39568561, 2024). "Taken together, VPS9D1-AS1/miR-324-5p/ITGA2 axis has been reported to affect pathogenesis of colorectal cancer." (PMID 36035118, 2022). "In line with the observed targeting of ITGA2 3′ UTR by miR-324-5p targets, miR-324-5p knock-down or forced over-expression of ITGA2 has reduced the impact of VPS9D1-AS1 silencing in colorectal cancer cells." (PMID 36035118, 2022). "ITGA2 was targeted by miR‐16‐5p, suppressed tumour proliferation, angiogenesis in the colorectal cancer." (PMID 32557953, 2020). "In colorectal cancer, antibodies specifically blocking ITGA2 inhibited focal adhesion kinase activation and cell motility." (PMID 32232000, 2020). "It has been reported that miR-16-5p inhibits tumor progression by down-regulating ITGA2 in colorectal cancer." (PMID 31818309, 2019).
liver cancer (11 papers, 2019 to 2025). An epithelial or non-epithelial malignant neoplasm that arises from the liver. "Kaplan-Meier analysis showed a clear association of high levels of COL1A1 and ITGA2 with poor prognosis of liver cancer patients (all P < 0.05)." (PMID 35322024, 2022). "Recent studies have increasingly reported abnormal ITGA2 expression across a range of malignancies, including gastric, pancreatic, breast, liver cancers, and glioma, where it plays a crucial role in various aspects of tumor initiation and progression." (PMID 41008552, 2025). "This study provides a novel therapeutic strategy of targeting ITGA2 to enhance lenvatinib efficacy, potentially contributing to more effective liver cancer treatments." (PMID 40940943, 2025). "To further explore the correlation between the expression level of ITGA2 and the sensitivity of liver cancer to lenvatinib, we conducted a series of cell experiments." (PMID 40940943, 2025). "Regression analysis using scatter plots showed that the lenvatinib IC50 values of liver cancer cells were significantly positively correlated with the expression level of ITGA2." (PMID 40940943, 2025). "Targeting ITGA2 can significantly increase the efficacy of lenvatinib and provides a new strategy to overcome liver cancer resistance." (PMID 40940943, 2025). "Strikingly, the levels of COL1A1, ITGA2, and YAP are associated with morphological heterogeneity and poor overall survival of liver cancer patients." (PMID 35322024, 2022). "In liver cancer, upregulation of ITGA2 by ADAR1 enhanced metastasis by increasing adhesion to the ECM." (PMID 32232000, 2020). "Consistent with the finding from RNA-seq analysis, ITGA2 silencing by two independent sh-RNAs decreased PD-L1 expression in pancreatic, breast, gastric, and liver cancer cells d,f." (PMID 31818309, 2019). "Results indicate that high ITGA2 levels increase lenvatinib resistance in liver cancer cells." (PMID 40940943, 2025). "For cirrhosis compared with NAFLD, the most significantly upregulated genes were related to liver cancer (ITGA2, GOLM1) and inflammation (ITGA2), inflammasome activation (JAG1), and fibrosis (JAG1)." (PMID 40489530, 2025). "There was a positive correlation between COL1A1/ITGA2 and YAP/CTGF in liver cancer patient (R2 = 0.35, P < 1.1e-12, R2 = 0.49, P < 2.2e-15)." (PMID 35322024, 2022). "Based on the analysis of 367 liver cancer patients from The Cancer Proteome Atlas (TCGA) database, the COL1A1 and COL1A2 signatures showed modest correlation with ITGA2 (R = 0.49, p < 2.2e-16, R = 0.51, p < 1.7e-12, Pearson’s correlation)." (PMID 35322024, 2022). "Additionally, physical juxtaposition staining patterns were observed for COL1A1, ITGA2, and YAP in diversity-high tumor tissues, indicating an interaction between TAF and tumor cells mediated by COL1A1-ITGA2 and YAP-signals in diversity-high liver cancer patients." (PMID 35322024, 2022).
hepatocellular carcinoma (10 papers, 2017 to 2025). A malignant tumor that arises from hepatocytes. "Reportedly, the loss of ADAR1 could lead to the up-regulation of ITGA2 in hepatocellular carcinoma." (PMID 31818309, 2019). "At the post-translational level, ADAR1 p110 enhances hepatocellular carcinoma cell adhesion to the extracellular matrix by upregulating ITGA2 expression." (PMID 40940943, 2025). "We explored the effect of the ITGA2 small molecule inhibitor E7820 on the drug sensitivity of liver cell carcinoma to lenvatinib to facilitate further clinical translation." (PMID 40940943, 2025). "Epigenetically, YY1 can recruit HDAC1 to form a repressor complex that downregulates HOXD3 expression, thereby suppressing the ITGA2 pathway in hepatocellular carcinoma cells." (PMID 40940943, 2025). "The ITGA2 inhibitor E7820 can promote lenvatinib-induced apoptosis and cell cycle arrest in hepatoma cells, thereby reversing lenvatinib resistance." (PMID 40940943, 2025). "Although this study has confirmed that ITGA2 mediates lenvatinib resistance in hepatocellular carcinoma via the AKT/FOXO3A signaling pathway, several limitations remain, and future studies should focus on the following aspects for further expansion." (PMID 40940943, 2025). "On the basis of in vitro and in vivo experiments, we confirmed that ITGA2 can lead to a decrease in the drug sensitivity of hepatocellular carcinoma to lenvatinib." (PMID 40940943, 2025). "In hepatocellular carcinoma cells, ITGA2 inhibits MST1 kinase phosphorylation and activates YAP pro-oncogenic activities." (PMID 32899691, 2020). "Compared with the control, knockdown of ITGA2 promoted apoptosis and cell cycle arrest, whereas overexpression of ITGA2 reduced apoptosis and cell cycle arrest, promoting cell growth and confirming that ITGA2 promotes lenvatinib drug resistance in liver cell carcinoma." (PMID 40940943, 2025). "ADAR1 also reportedly enhances hepatocellular carcinoma (HCC) metastasis by promoting tumor cell adhesion to ECM via increasing ITGA2 expression." (PMID 31818309, 2019). "Specifically, in hepatocellular carcinoma (HCC) patients with high ITGA2 expression, a first-line treatment strategy combining lenvatinib with an ITGA2 inhibitor may potentially prevent or delay the acquisition of drug resistance." (PMID 40940943, 2025). "Cell Counting Kit-8 (CCK-8) and Western blotting (WB) experiments confirmed the correlation between ITGA2 expression and the IC50 of lenvatinib in hepatoma cell lines." (PMID 40940943, 2025). "Therefore, our results suggest that ITGA2 activates the AKT/FOXO pathway by regulating its phosphorylation level and mediates lenvatinib resistance in hepatocellular carcinoma." (PMID 40940943, 2025). "However, to date, no studies have explored the role of ITGA2 in the sensitivity of liver cell carcinoma to lenvatinib or the mechanism involved." (PMID 40940943, 2025).
lung cancer (10 papers, 2013 to 2025). A malignant neoplasm involving the lung. "In addition to down-regulating Rho GTPases, we found EL elevated ITGA2 mRNA expression in lung cancer cells." (PMID 28068967, 2017). "Therefore, EL-induced ITGA2 expression may anchor lung cancer cells to the matrix and prevent cell migration." (PMID 28068967, 2017).
diabetes (9 papers, 2008 to 2024). "Other studies demonstrated that ITGA2 C807T SNPs were associated with carotid IMT plaque and had a higher risk of ischemic stroke in patients with type 2 diabetes mellitus." (PMID 38827573, 2024). "A case-control study was performed to study the genetic association between DR and polymorphic variants of EDN1 (Lys198Asn), LTA (IVS1–80C>A, IVS1–206G>C, IVS1–252A>G), eNOS (Glu298Asp), and ITGA2 (BgI II) in a Chinese population with type 2 diabetes mellitus." (PMID 18806884, 2008).
glioma (9 papers, 2021 to 2025). A benign or malignant brain and spinal cord tumor that arises from glial cells (astrocytes, oligodendrocytes, ependymal cells). "A recent study has demonstrated that loss of ITGA2 reduces glioma cell proliferation, invasion, and adhesion, and can be targeted to overcome radio- and chemo-resistance, ultimately improving patient survival." (PMID 41008552, 2025). "Moreover, a number of studies have shown that the loss of ITGA2 can reduce the proliferation, invasion and adhesion of glioma cells, and can be targeted to overcome the resistance of glioma cells to radiotherapy and chemotherapy, thereby prolonging the survival of patients." (PMID 39568561, 2024). "ITGA2 is enriched in glioma stem-like cells to promote invasion by modulating PD-L1 and activating STAT3 phosphorylation, enhancing epithelial-mesenchymal transition." (PMID 40885689, 2025). "Similar to our findings, ITGA2 has been shown to be enriched in glioma stem cells and co-expressed with the stem cell marker SOX2." (PMID 40316546, 2025). "We found that the genotypes of ITGA2 BglII for gliomas and control individuals were distributed in accordance with the Hardy–Weinberg equilibrium and in agreement with those previously published to Caucasian subjects." (PMID 35936750, 2022). "This also makes ITGA2 an attractive target for the treatment of glioma." (PMID 39568561, 2024). "Based on TCGA database, we analyzed the expression of ITGA2 on gliomas." (PMID 35936750, 2022). "Furthermore, we analyzed the potential impact of ITGA2 on the overall survival of glioma grade II, III, and IV patients using the same database (TCGA)." (PMID 35936750, 2022). "Nonetheless, the role of ITGA2 in glioma tumor is still not well understood." (PMID 35936750, 2022). "However, changes in ITGA2 expression may affect therapeutic targets, immune microenvironment, and the immunogenicity of glioma tumors." (PMID 35936750, 2022). "We studied 998 glioma samples from TCGA and CGGA cohorts to validate ITGA2 as a novel biomarker for LGG in both cohorts." (PMID 34778054, 2021).
ischemic stroke (9 papers, 2019 to 2024). A stroke disorder caused by obstruction of blood flow to the brain, due to thrombotic (local blood clot formation) or embolic (due to a blood clot or other material traveling from another site) event. "The gene encoding ITGA2 contains a number of polymorphisms, such as ischemic stroke and idiopathic sudden sensorineural hearing loss (iSSNHL)." (PMID 33557870, 2021). "Genetic variants associated with higher platelet surface integrin α2 (ITGA2) receptor levels have frequently been found to correlate with an increased risk of ischemic stroke in patients." (PMID 31022936, 2019). "Furthermore, ITGA2 polymorphism was associated with the risk of ischemic stroke, carotid intima‐media thickening, and plaques in patients with type 2 diabetes." (PMID 37137812, 2023). "The ITGA2 gene polymorphism may be a susceptible predictor of the risk of ischemic stroke." (PMID 36686520, 2022). "SNPs of ITGA2 C807T were associated with carotid IMT, plaque, and the risk of ischemic stroke in patients with type 2 diabetes." (PMID 37292135, 2023). "Fourth, although we found that the high-risk interactive genotypes in ITGA2 rs1991013, IL1A rs1609682, and HABP2 rs7923349 independently increased ischemic stroke and other vascular events, the detailed molecular mechanisms remain unclear." (PMID 38827573, 2024). "Furthermore, we found a significant gene–gene interaction among ITGA2 rs1991013, IL1A rs1609682, and HABP2 rs7923349, and the high-risk interactive genotypes in the three SNPs independently increased ischemic stroke and other vascular events." (PMID 38827573, 2024). "Furthermore, we identified the specific SNPs and interaction among IL1A rs1609682, ITGA2 rs1991013, and HABP2 rs7923349 in genes involved in inflammation and endothelial function increased the risk of carotid atherosclerosis, ischemic stroke, and composite vascular events." (PMID 38827573, 2024). "Our results underscore that GPVI, but not ITGA2, is a promising and safe target in the setting of ischemic stroke." (PMID 31022936, 2019).
COVID-19 (7 papers, 2021 to 2023). A disease caused by infection with severe acute respiratory syndrome coronavirus 2. "The purpose of this study was to investigate the association between soluble ITGa2, ITGaM and ITGb2 integrin subunits and long COVID-19 pulmonary complications." (PMID 36615143, 2023).
metastatic disease (7 papers, 2017 to 2024). "Next, we examined whether ITGA1/ITGA2 copy loss directly correlates with PCa metastasis in two independent cohorts of PCa patients with primary and metastatic tumors." (PMID 38169150, 2024). "In the present study, even the direction of the mRNA expression was similar for ITGA3, we observed significant decrease only for the ITGA2 gene in the metastatic tumors." (PMID 36091936, 2022). "The relative expression of eight integrins was very low; only ITGB3 showed detectable expression in metastatic tumors compared to the primary lesions; moreover, ITGA2 showed significant negative correlation with the Breslow thickness of the primary tumors." (PMID 36091936, 2022).
osteosarcoma (7 papers, 2016 to 2023). A usually aggressive malignant bone-forming mesenchymal neoplasm, predominantly affecting adolescents and young adults. "However, Dedhar and Saulnier showed that the expression of ITGA2/B1 increased in the chemically transformed human osteosarcoma cells, and this integrin was implicated in tumour progression and metastasis." (PMID 33276802, 2020).
papillary thyroid carcinoma (7 papers, 2018 to 2025). "Papillary thyroid cancer cells are inhibited from migrating, invading, and proliferating because ropivacaine inhibits ITGA2 activation." (PMID 40713692, 2025). "MiR-99a-3p also affected metastasis of papillary thyroid carcinoma by accommodating integrin subunit alpha 2 (ITGA2) expression and localization." (PMID 35884594, 2022). "Ropivacaine hinders migration, invasion, and proliferation and increases apoptosis of papillary thyroid cancer cells via ITGA2." (PMID 34126594, 2021). "Although ITGA2 has been shown to be a target gene for certain microRNAs in aggressive papillary thyroid carcinoma, the impact and significance of its increased expression in follicular thyroid carcinoma cells upon PROX1 silencing, like that of the ITGA11 downregulation, remains to be clarified." (PMID 31060342, 2019). "MiR-99a-3p targets integrin subunit alpha 2 (ITGA2), affecting metastasis in papillary thyroid carcinoma." (PMID 38720056, 2025). "The expression of biomarkers (ITGA2, SYT12 and CDH3) was studied in a prospective cohort of patients with papillary thyroid cancer." (PMID 29255621, 2018).
type 2 diabetes (7 papers, 2008 to 2024). "For example, ITGA2 (integrin alpha-2) triggers inflammation and endothelial dysfunction in patients with cardiovascular disease, chronic kidney disease, and type-2 diabetes, and joint inflammation in mouse models of rheumatoid arthritis." (PMID 30038668, 2018).
atherosclerosis (6 papers, 2020 to 2024). A disease characterized by the build-up of fatty material and calcium deposition in the arterial wall resulting in partial or complete occlusion of the arterial lumen. "ITGA2 rs1991013 was associated with carotid calcified plaque and increased risk of general atherosclerosis." (PMID 37292135, 2023). "But a study about Dominicans found that ITGA2 rs1991013 is associated with calcified plaque and increases the risk of general atherosclerosis." (PMID 36686520, 2022). "In rat atherosclerosis PCR array, Abca1, Bax, Bcl2, Bcl2a1, Cd44, Fabp3, Hbegf, Lypla1, Ptgs1, Selplg, Tgfb2, Tnc, and Vegfa had reverse trend between WT and MU groups, while the trends of Bcl2l1, Bid, Birc3, Cxcl1, Fas, Fn1, Itga2, Itga5, Lif, Nfkb1, Nr1h3, Ppard, and Sod1 were consistent." (PMID 34545275, 2021).
esophageal squamous cell carcinoma (6 papers, 2021 to 2025). Esophageal squamous cell carcinoma (ESCC) is a type of esophageal carcinoma (EC) that can affect any part of the esophagus, but is usually located in the upper or middle third. "Overexpression of ITGA2 increases the aggressiveness of esophageal squamous cell carcinoma through the Akt signaling pathway." (PMID 38028209, 2023). "Regarding the potential molecular mechanism underlying this phenomenon, a previous study reported that ITGA2 silencing inhibits FAK/AKT signaling, thereby decreasing cell proliferation in esophageal squamous cell carcinoma." (PMID 36765586, 2023). "For example, Integrin Subunit Alpha 2 (ITGA2) was found to affect cell motility in esophageal squamous cell carcinoma by regulating the focal adhesion kinase/protein kinase B (FAK/AKT) axis." (PMID 34572451, 2021).
lung adenocarcinoma (6 papers, 2016 to 2025). A carcinoma that arises from the lung and is characterized by the presence of malignant glandular epithelial cells. "Recent results have indicated that ITGA2 activated the FAK-RAC1-PAK signaling pathway to participate in the formation of the cytoskeleton in lung adenocarcinoma cells and then promoted migration and invasion." (PMID 39940682, 2025). "At the transcriptional level, BACH1 can promote lung adenocarcinoma cell metastasis by directly activating ITGA2 transcription, and KLF7 has been shown to regulate ITGA2 expression to maintain oral cancer stem cell properties." (PMID 40940943, 2025). "As expected, EGFR, ITGA2, KRAS, MMP9, NRAS and MAPK13 had higher levels in lung adenocarcinoma than in normal lung tissues." (PMID 32210363, 2020).
Arthritis (5 papers, 2014 to 2022). Inflammation of a joint. "In the present result, it was observed that a single gene is associated with different types of diseases as ITGA2 is involved in arthritis, chronic kidney disease and eye disease." (PMID 28587194, 2017).